CD8A (CD8 subunit alpha)
Diseases named in the same sentence as CD8A in open-access papers (continued):
Sharing a sentence is not in itself a finding about the gene and the disease.
cancer (continued). "As with TCGA Pan-Cancer Atlas data, patients with below-median PI24 scores expressed high levels of immunoglobulin genes, CD8A, and chemokine genes (CCL4, CCL5, and CXCL10), and had significantly higher PFS and OS rates (P = 0.00041 and P = 0.0011, respectively)." (PMID 36099049, 2022). "Next, we compared CD8A’s predictive ability for immunotherapy efficacy to other canonical biomarker signatures in TIDE database, using treatment response and survival outcomes from various cancer cohorts treated with ICB." (PMID 36035168, 2022). "Notably, our study demonstrated the predictive potential of CD8A in antitumor compounds or agents, with the results based on GDSC and CTRP databases uniformly presenting close correlations between CD8A and IC50 of such agents to cancer cell lines." (PMID 36035168, 2022). "Interestingly, CD8A, CD8B, TCF7, and LEF1 cannot serve as therapeutic targets for these cancers because of their different expression profiles." (PMID 35588138, 2022). "Thus, the DNA methylation differences of CLEC5A and immune-related gene (MRC1, CD163, CD8A, CD8B, CD68) between tumors and normal tissues in various cancers were evaluated with the GSCALite platform." (PMID 35979347, 2022). "The results above denoted that CD8A manifested a negative correlation with multiple cancer-related functional states, indicating that CD8A exerts antitumor effects and maintains cancer immunity in UVM." (PMID 36035168, 2022). "Besides, epigenetic modifications of CD8A were related to CTL levels and T cell dysfunctional states, thereby affecting survival outcomes of specific cancer types." (PMID 36035168, 2022). "CD8A expression was correlated with all three genes in 22 cancer types, and with IDO-1 and IDO-2 (but not TDO-2) in nine more cancer types, so CD8+ T-cell infiltration is likely a widespread predictor of IDO pathway over-expression." (PMID 34367262, 2021). "CD8A expression is correlated with all three genes in 22 cancer types, and with IDO-1 and IDO-2 (but not TDO-2) in nine more cancer types, so CD8+ T-cell infiltration is likely a widespread predictor of IDO pathway over-expression." (PMID 34367262, 2021). "This assay enables to interrogate single cell expression levels of multiple mRNA of interest such as CD4, Cd8α, IFNγ and GZMB and their spatial distribution and can be used to detect, quantitate and evaluate the frequency and function of CAR T cells and cancer cells in tissues." (PMID 34155235, 2021). "Failure of CD8α+ T cells in blocking cancer growth is probably due to the cell not functionally activated." (PMID 31752354, 2019). "CD8α DC are particularly potent at phagocytosing dying cells for antigen cross-presentation and at inducing CTL responses, being thus one key target for vaccines against cancer and infectious diseases." (PMID 21674051, 2011). "Both T cell markers (PD-1, CD8A, and CD8B) and immune checkpoint blockade PD-L1 show increased expression in samples with SCMs compared to samples without SCMs, indicating alternative splice forms induced by SCMs increase the overall immunogenicity of these cancers." (PMID 29617666, 2018). "The elevated level of Granzyme b in the CD8a+ T cells and the increased cellular killing seen by microscopy further indicates that the CTL effector mechanisms have been heightened in the presence of ILC2s, providing a mechanism for ILC2 action in anti-cancer immunity." (PMID 29440650, 2018). "In CD8+ T cells xCell was outperformed by methods depending solely on CD8A expression, which may not serve as a reliable biomarker in cancer settings." (PMID 29141660, 2017). "Therefore, immunotherapy that involves the activation of both CD8α+CD11c+ and CD8α−CD11c+ cDCs by cancer Ags combined with an adjuvant may elicit both CTL and Th immune responses against cancer cells, thereby improving the efficacy of the treatment." (PMID 27341129, 2016).
cancer (continued). "Interestingly, we observed not only an overall increase in CXCL9 in cancer, but also a significant increase in ER‐negative subtypes compared to luminal A cancers, and these levels correlated significantly with levels of the TIL‐related markers CD8A, CD4, and CD5." (PMID 30019538, 2018). "A rare population of NY-ESO-1-specific T cells, which we named 19305DP, expressed cell surface CD4, CD8α, and CD8β but not CD56 and recognized A*02+NY-ESO-1+ cancer cell lines in a CD4- and CD8-independent manner." (PMID 30626427, 2019). "GEMM-derived tumors, GEK1425 and GEK1428, and the non-responsive carcinogen-induced carcinoma, CCK62, showed very little infiltration by T cells (CD3+ or CD8a+), and this was largely unaltered by therapy." (PMID 30832732, 2019). "In general, CD8α/α and double-negative human NKT cells are considered of similar functionality; these cells are proinflammatory and exhibit heightened cytotoxicity, making them desirable for cancer immunotherapy." (PMID 38744947, 2025). "Four fibroblast groups co-inoculated with cancer cells were compared: no treatment (control), treated with MR16-1 (MR16-1), treated with anti-CD8α antibody (anti-CD8α), and treated with MR16-1 and anti-CD8α (MR16-1 + anti-CD8α)." (PMID 36764954, 2023).
infection (7,288 papers, 2004 to 2026). The state of being infected such as from the introduction of a foreign agent such as serum, vaccine, antigenic substance or organism. "For example, results from Roxane Tussiwand and colleagues show that both in vitro and in vivo experiments demonstrate that BATF3-deficient cells or mice retain a portion of the normal CD8α+DC population and function, allowing them to resist infections." (PMID 39876010, 2025). "Research indicates that BATF3 deficiency affects the cross-presentation capability of CD8α+DCs during infections, resulting in functional impairment." (PMID 39876010, 2025). "In order to study the involvement of CD8+ T cells in the early immunoprotection of NO-deficient mice, CD8α+ cells were in vivo depleted by monoclonal antibodies, and the severity of infection characterized at week 2 postinfection." (PMID 23936574, 2013). "We demonstrate that CD8α+ DCs are the most susceptible to infection ex vivo and the only subset capable of priming antigen specific T cells to Lm." (PMID 21559416, 2011). "Taken together, Ye stimulates increased proliferation of DCs, but higher cell death rates combined with inhibition of de novo generation lead to loss of CD4+ and CD8α+ DC subsets upon infection." (PMID 21124820, 2010). "Not surprisingly, immune genes and immune pathways are frequently identified as being associated with differential response to infection in this model, and differentially expressed genes such as CD8α, IL8, CTLA-4, IL17A, and IL12Rβ2 implicate T cell transcriptional pathways in MD resistance." (PMID 36992316, 2023). "Moreover, early depletion of CD8α+ cells during infection is strongly associated with reduced bacterial clearance." (PMID 30001716, 2018). "Previous studies have implicated CD8 α+ DC in the presentation of all viral antigen, but these studies may reflect preferential infection of certain DC subpopulations by viruses, or exclusive presentation of exogenous antigen as pAPC are not infected." (PMID 26107264, 2015). "However, the cross-presentation capacity of CD8α+ DCs is a double-edged sword, as it also increases their susceptibility to infection." (PMID 24695322, 2014). "Indeed, at steady state, we observed that a lot of potential DCs (KUL01+, MHC-II+, and CD11c+) reside in the lung, which could be associated with the local response of γδ T cell and CD8α+ T cells in the lung after infection." (PMID 33291218, 2020). "We favor two non-mutually exclusive explanations of this finding: the CD8α TM domain facilitates less HIV fusion than the CD4 TM domain, making cells less susceptible to CD4 CAR-mediated infection; and the CD8α TM domain promotes dimerization, which may potentiate signaling." (PMID 29023549, 2017). "Previous studies reported that infection with the RB-1B strain increases CD8α+ γδ T cells (TCRγδ+CD3+CD8α+) during the transformation phase, suggesting a role for this subset in responding to infected or transformed cells." (PMID 40733525, 2025). "(B) Representative images and (C) quantification of epidermal whole mounts of VV and DNFB treated flanks harvested on day 50 post infection stained for CD8a." (PMID 41468295, 2025). "A study has indicated that OT-I CD8+ T cell expansion is impaired in aged mice during infection, which further selectively influences CD8α+ DC." (PMID 40379629, 2025). "In the spleens and PBMCs of rMDV-infected chickens, increases in CD8α+ T and γδ T cells were observed during early infection." (PMID 40733525, 2025). "We also monitored changes in the colocalization of HIV DNA and CPSF6 during infection and entry of cells into quiescence after infection with the pHR′-CD8a-d2EGFP virus." (PMID 38669184, 2024). "In accord, we observed increased Il-10, Cd4, Cd8a, and Foxp3 mRNAs in our RNA-seq data from K-RasLA1 mice on day 7 post-infection." (PMID 39338937, 2024).
infection (continued). "(2007) also indicated that EVs produced by SRDC (a CD8α+CD4− dendritic cell line) treated with T. gondii antigens induced protection against infection in vivo." (PMID 39113589, 2024). "PEP-619WW mice had more pDCs (PDCA-1+ B220+ Ly6C+ CD8α- CD11c+/- DCs) following infection, compared to mock infected animals." (PMID 38512979, 2024). "It was also described that the population of CD8α+ intraepithelial lymphocytes (CD8α+ IEL) in the crypts of the jejunum decreased significantly 2–3 weeks after infection." (PMID 37773698, 2023). "Conversely, infection significantly increased the frequency of CD3ζ + CD8α + αβ T cells across all segments of the intestine when compared to the rL. lactis treated and infected chickens." (PMID 38164397, 2023). "Previous studies have established that CD8α+ dendritic cells (cDC1) are the obligate cellular entry points for productive infection by intracellular bacterium L. monocytogenes." (PMID 37863917, 2023). "We found that SARS-CoV-2 CD8a peptide induced glut-1 expression in CD8+Tc from severe COVID(+) patients, suggesting that glucose metabolism is associated with SARS-CoV-2-specific CD8+Tc during infection." (PMID 37029220, 2023). "The CD8 α+ cells were more abundant in vaccinated groups before infection and significantly increased in all groups post infection, especially the control group that maintained at relatively high level." (PMID 36969197, 2023). "We found that genes associated with antiviral immune responses to RNA viruses, including Mx, Gig2 and Viperin, were upregulated in the early phase of infection, followed by increased expression of CD8α and GZMa in the later stage." (PMID 36694262, 2023). "Infection with C. perfringens also led to a significant increase in the frequency of CD3ζ + CD8α + γδ T cells in duodenum (p ≤ 0.01), ileum (p ≤ 0.05) and cecal tonsils (p ≤ 0.005)." (PMID 38164397, 2023). "Infusion of TCRγδ-activated PBMCs induced IFN-γ-producing γδ T cells at 10 days post-infection (dpi), and degranulation activity in circulating γδ T cell and CD8α+ γδ T cells at 10 and 21 dpi in MDV-challenged chickens." (PMID 36851499, 2023). "Head kidney gene expression showed a down-regulation of il1β at 4 h and cd8α at 48 h following infection in fish fed TRP, while presenting a higher expression of tnfα at 24 h than that of the CTRL-fed fish." (PMID 36293344, 2022). "Regarding the lymphocyte markers, the transcription of the T cells, tcrb, and cd8a was down-regulated during infection in both the gills and in the HK, whilst the marker cd4 was not altered." (PMID 35055122, 2022). "NK-cell depletion significantly reduced the number of CD103+CD11b– DCs expressing CD86 or CD8α following T1L infection, but the frequency of these populations remained unchanged." (PMID 35993365, 2022). "The results highlighted the potential role of CD4 CTL and CD4/CD8α DN cells in protection against transplacental infection." (PMID 36798517, 2022). "Infection induced significant changes in the percentage of CD4+CD8α+ T cell subpopulations in the blood of turkeys (P = 0.021)." (PMID 35883183, 2022). "In turn, the percentage of CD4+CD8α+ double positive T cell subpopulations in the spleen of turkeys was significantly affected by infection, and it was higher in birds challenged with C. perfringens than in those administered LPS (P = 0.032)." (PMID 35883183, 2022). "Infection with moderately virulent Estonia2014 induced significant increases in the frequency of CD8α+ CTLs 5–10 dpi, especially in spleens, lungs, and livers of infected domestic pigs." (PMID 35215216, 2022). "This was in contrast to previous data with the virulent Armenia strain of the virus, where elevated numbers of CD4+CD8α cells were observed five days post-infection." (PMID 35891467, 2022).
infection (continued). "In contrast to this, in vaccinated carp under challenge infection, both cd8a genes were >three-fold upregulated to a level, which resulted in a statistically significant difference between challenged vaccinated and non-vaccinated fish." (PMID 35173716, 2022). "It has been reported that CD8 + cells expressing the CD8-α chain are involved in elimination of IBV-infected cells during early infection." (PMID 34772449, 2021). "We used a nanobody that recognizes mouse CD8α and labeled it with 89Zr to image mouse CD8+ T cells in the course of an infection with influenza A virus (IAV)." (PMID 34804069, 2021). "L. donovani infected DCs start producing IL-12, IL-23 and IL-27 within 5 hours of infection, IL-12 being mostly produced in CD8α+ DC subsets." (PMID 34712235, 2021). "In such study, it was found that contrary to the classical view that LCs initiate T cell priming at the draining lymph nodes, it was the CD8α+ DC subset that activated virus-specific cytotoxic T cells in the brachial lymph nodes 2 days after a flank infection." (PMID 34895058, 2021). "A similar analysis of the acute-infection dynamics in the RMs in the CD8α depletion-plus-AZD5582 group was performed." (PMID 33568515, 2021). "Our results make it clear that the proportion of CD8α+ tetramer+ double positive T cells continues to rise during infection, proving that the specific CD8+ T cell immune response has been activated during ASFV infection." (PMID 34835070, 2021). "At day 12 post infection, the observed increase in gene expression of CD8a, CD8b, and FasL mRNA indicates that the cytotoxic T cell pathway was upregulated in the colon of Cr-infected mice." (PMID 32230738, 2020). "Because CD4 and CD8 T cells also play an important role in adaptive immune responses, we assessed changes in the CNS levels of Cd4, Cd8a, and Cd8b mRNAs after infection as indicators of T cell infiltration and retention." (PMID 32047134, 2020). "The frequencies of IL-12p40+ CD8α+ and CD11b+ DCs increased to a similar extent after infection in wt and C5ar1−/− mice." (PMID 32733463, 2020). "The expression of cytotoxic T cell markers CD8a, CD8b, and FasL mRNA were upregulated by the infection with Cr in colonic tissue." (PMID 32230738, 2020). "As such, the role of cDC1 in the transit of InlAMLm and establishment of productive infection after foodborne infection was evaluated in Batf3–/– mice, which lack resident CD8α+ and migrant CD103+ cDC1." (PMID 33042159, 2020). "In the liver following infection, NK cells, pDCs, CD8α+ DCs and CD8+ T cells were significantly increased in WT mice and NK cells, as were CD8α+ DCs and F4/80hi CD11blo macrophages in RAG1 KO mice." (PMID 32310998, 2020). "Batf3−/− mice, which lack CD8α+ and CD103+ cDCs, are therefore highly susceptible to infection with T. gondii due to inadequate early IL-12 production." (PMID 32669460, 2020). "• Infection promotes the IL-27 expression by splenic CD8α+ and CD4+ DC at days 1, 14, and 28 post-infection." (PMID 32849534, 2020). "Batf2 play regulatory role in CD8α + classical DC development and contributes to anti-T. gondii in vivo infection." (PMID 31333663, 2019). "Seven days after immunization or infection, both anti-CD8α and –β surviving OT1 T cells had readily detectable mAbs bound, confirmed directly by staining for rat IgG." (PMID 30735510, 2019). "In CD8α-depleted rats, however, virus control was delayed until blood CD8+ T cells began to recover at 28 days post infection." (PMID 30846697, 2019). "Treatment of rats with anti-CD8α antibody (−2, 5, and 12 days post infection) resulted in >99.9% depletion of blood CD8+ T cells at time of challenge compared to IgG1 controls." (PMID 30846697, 2019). "Three days after infection, CD8a-expressing cells were isolated and then allowed to expand up to 50-fold for 7 to 10 days." (PMID 30914509, 2019). "The cysteine residues of free ISG15 are required to trigger an increase in CD8α+ DCs producing IL-1β at the site of the infection." (PMID 29891555, 2018).